SNX2 (sorting nexin 2)
Description:
Involved in several stages of intracellular trafficking. Interacts with membranes containing phosphatidylinositol 3-phosphate (PtdIns(3P)) or phosphatidylinositol 3,5-bisphosphate (PtdIns(3,5)P2). Acts in part as component of the retromer membrane-deforming SNX-BAR subcomplex. The SNX-BAR retromer mediates retrograde transport of cargo proteins from endosomes to the trans-Golgi network (TGN) and is involved in endosome-to-plasma membrane transport for cargo protein recycling. The SNX-BAR subcomplex functions to deform the donor membrane into a tubular profile called endosome-to-TGN transport carrier (ETC) (Probable). Can sense membrane curvature and has in vitro vesicle-to-membrane remodeling activity. Required for retrograde endosome-to-TGN transport of TGN38. Promotes KALRN- and RHOG-dependent but retromer-independent membrane remodeling such as lamellipodium formation; the function is dependent on GEF activity of KALRN.
Synonyms: TRG-9
Tractability: Antibody: UniProt places it where antibodies can reach, with high confidence. PROTAC: ubiquitination databases record sites on it; its protein half-life has been measured.
Gene: Protein-coding gene on chromosome 5 (122,775,010 to 122,834,543, forward strand). Ensembl gene ENSG00000205302.
Subcellular location: Early endosome membrane; Cell projection, lamellipodium
Subcellular location (Human Protein Atlas): Endosomes; Lysosomes
Pathways (Reactome):
Vesicle-mediated transport: Golgi Associated Vesicle Biogenesis
Gene Ontology:
Molecular function: cadherin binding; epidermal growth factor receptor binding; identical protein binding; insulin receptor binding; leptin receptor binding; protein binding; protein heterodimerization activity; protein homodimerization activity; transferrin receptor binding; phosphatidylinositol binding
Biological process: lamellipodium morphogenesis; retrograde transport, endosome to Golgi; endosomal transport; intercellular transport; intracellular protein transport
Cellular component: cytoplasm; endosome; endosome membrane; membrane; protein-containing complex; retromer complex; retromer, tubulation complex; cytosol; early endosome membrane; lamellipodium
Genetic constraint (gnomAD): Loss-of-function variants: 13 observed, 39.67 expected, observed/expected ratio (o/e) 0.33, 90% interval 0.21 to 0.52. The upper end of that interval is the gene's LOEUF score, 0.52, which puts it in group 2 of 6, group 1 being the genes least tolerant of losing a copy. Missense variants: 349 observed, 438.19 expected, observed/expected ratio (o/e) 0.8, 90% interval 0.73 to 0.87. Synonymous variants: 149 observed, 138.69 expected, observed/expected ratio (o/e) 1.07, 90% interval 0.94 to 1.23.
Homologues: Orthologues: chimpanzee SNX2 (99% identical), dog SNX2 (98% identical), guinea pig SNX2 (97% identical), mouse Snx2 (97% identical), pig SNX2 (97% identical), macaque SNX2 (97% identical), rat Snx2 (97% identical), rabbit SNX2 (92% identical), tropical clawed frog snx24 (80% identical), zebrafish snx2 (54% identical), Drosophila melanogaster Snx1 (43% identical), Caenorhabditis elegans snx-1 (33% identical), and 2 more. Paralogues in human: SNX1 (60% identical), SNX18 (20% identical), SNX33 (18% identical), SNX7 (18% identical), SNX30 (17% identical), SNX4 (17% identical), SNX32 (16% identical), SNX6 (16% identical), SNX5 (16% identical), SNX9 (15% identical), SNX8 (15% identical), SNX11 (12% identical), and 3 more.
Diseases named in the same sentence as SNX2 in open-access papers:
SNX2 is named in the same sentence as 18 diseases in open-access papers, as found by Europe PMC text mining. Sharing a sentence is not in itself a finding about the gene and the disease. The quoted sentences say what the papers report.
lung carcinoma (4 papers, 2017 to 2026). "Studies using siRNA-mediated down-regulation of SNX1 and SNX2 suggest their involvement in regulating MET signaling in lung cancer cells." (PMID 38836326, 2024). "SNX2 regulates c-Met trafficking and modulates sensitivity to targeted therapies in lung cancer." (PMID 41487280, 2026). "Lung cancer cells exhibit hyperphosphorylation of the corresponding serine in SNX1, SNX2, SNX3, and SNX2136,39." (PMID 29520003, 2018).
colorectal cancer (3 papers, 2017 to 2024). A primary or metastatic malignant neoplasm that affects the colon or rectum. "CAF-derived exosomal miR-181b-3p promotes colorectal cancer progression by decreasing the expression of the sorting nexin 2 (SNX2) gene." (PMID 37242707, 2023). "Finally, we show that SNX2 mRNA and protein levels are decreased in colorectal carcinoma and that lower SNX2 gene expression correlates with an increase in cancer patient mortality." (PMID 28179995, 2017). "Specifically, strong evidence points to the involvement of sorting nexins (SNXs), particularly SNX1 and SNX2, in the signaling and trafficking of the receptor tyrosine kinase (RTK) MET in colorectal cancer (CRC)." (PMID 38836326, 2024). "Finally, we show that depletion of SNX2 potentiates Met phosphorylation and signaling and that the expression of SNX2 is reduced in human colorectal carcinoma (CRC)." (PMID 28179995, 2017).
osteosarcoma (2 papers, 2022 to 2023). A usually aggressive malignant bone-forming mesenchymal neoplasm, predominantly affecting adolescents and young adults. "To this end, we performed double knockout (KO) of SNX1 and SNX2 (SNX1-2), and SNX5 and SNX6 (SNX5-6), in the human osteosarcoma cell line HT1080." (PMID 37322239, 2023). "At present, no investigations are reporting the role of SNX2 in osteosarcoma." (PMID 36569871, 2022).
Alzheimer disease (1 paper, 2009). A progressive, neurodegenerative disease characterized by loss of function and death of nerve cells in several areas of the brain leading to loss of cognitive function such as memory and language. "Depletion in humans of other, related, retromer subunits, Vps26 and Vps35, which require either SNX1 or SNX2 in order to associate with endosomes, increases amyloid-β peptide production associated with Alzheimer's disease." (PMID 19309515, 2009).
breast carcinoma (1 paper, 2022). "Our analysis confirmed the down-regulation of RPL13, and newly identified down-regulation of HDAC1, ANP32A, and the up-regulation of SNX2 as having the worst prognostic effects in normal-subtype breast cancer tumors (panels C4–C7)." (PMID 35971177, 2022).
colon cancer (1 paper, 2022). "SNX2 might play a tumor suppressing role in liver cancer and colon cancer." (PMID 35715463, 2022).
prostate carcinoma (1 paper, 2015). A carcinoma that arises from epithelial cells of the prostate gland. "A prostate cancer related module was investigated (due to its significant enrichment on KEGG prostate cancer pathway), which has DEGs as PDGFRB, PDGFB, SNX2, EGFR and DECGs as (PDGFRA, PDGFRB), (SNX4, PDGFRB), (PDGFB, PDGFRA), (SNX2, PDGFRA), (PDGFRB, PIK3R2), (EGFR, PIK3R2), (EGFR, AREG)." (PMID 26070628, 2015).
tumor (4 papers, 2013 to 2022). "The exacerbation of Met signaling following SNX2 reduction suggests a potential role in CRC tumor development." (PMID 28179995, 2017). "Therefore, tumor samples from 24 patients of all CRC stages were analyzed for SNX2 protein and compared with adjacent normal tissues." (PMID 28179995, 2017). "Aggregation of all tumor stages shows a significant reduction in SNX2 protein." (PMID 28179995, 2017). "We found that the ectopic expression of SNX16 but not SNX2 significantly reduces the tumor formation activity of MCF-7 cells (P=0.001, 0.0002 and 0.27 for SNX16-1, SNX16-2 and SNX2 respectively)." (PMID 25408875, 2013).
cancer (3 papers, 2017 to 2024). A tumor composed of atypical neoplastic, often pleomorphic cells that invade other tissues. "The ability of SNX2 to reduce Met signaling suggests a possible role for this protein in cancer development." (PMID 28179995, 2017).
infection (2 papers, 2020). The state of being infected such as from the introduction of a foreign agent such as serum, vaccine, antigenic substance or organism. "While we were able to identify protein spots for each complex, Rab1a-Dynll1, Snx2-Dynll1, and Canx-Dynll1 were not measurably altered by infection." (PMID 32041786, 2020).
SNX2 also shares sentences with these, for which no sentence is quoted: acute lymphoblastic leukemia (1 paper); acute myeloid leukemia (1); bladder cancer (1); chlamydial infection (1); COVID-19 (1); head and neck squamous cell carcinoma (1); liver cancer (1); non-small cell lung carcinoma (1).